GAS5 (growth arrest specific 5)
Diseases named in the same sentence as GAS5 in open-access papers (continued):
Sharing a sentence is not in itself a finding about the gene and the disease.
renal fibrosis (continued). "It was reported that FTO plays a role in regulating renal fibrosis, and the m6A modification of lncRNA GAS5 may participate in the process." (PMID 36685533, 2022). "Among these factors, urinary GAS5 had the highest correlation coefficient, suggesting a potentially greater impact on renal fibrosis, indicating that urinary GAS5 may serve as a potential biomarker for renal fibrosis." (PMID 40685500, 2025). "The cutoff value for urinary GAS5 was 0.235 (sensitivity 88.32%, specificity 80.33%), which could serve as a noninvasive diagnostic threshold to distinguish patients with renal fibrosis from non-fibrotic individuals in clinical practice." (PMID 40685500, 2025). "Importantly, pairwise analyses confirmed statistically significant differences between all adjacent fibrotic stages (mild vs moderate: p = 0.003; moderate vs severe: p < 0.001), establishing a robust inverse correlation between urinary GAS5 levels and histological progression of renal fibrosis." (PMID 40685500, 2025). "This prospective cross-sectional study quantified GAS5 levels in paired plasma and urine samples from 198 CKD patients (stratified by renal fibrosis scoring: mild: <25%, moderate: 25–50%, severe: ≥50% fibrotic area) and 20 healthy controls." (PMID 40685500, 2025). "Quantitative analysis revealed a statistically significant elevation in plasma GAS5 expression levels within the renal fibrosis cohort compared to both healthy controls (p < 0.001) and non-fibrotic pathological controls (p < 0.001)." (PMID 40685500, 2025). "Our study findings revealed that urinary GAS5 levels exhibited a negative correlation with the presence and severity of renal fibrosis." (PMID 40685500, 2025). "In addition to the nephroprotective role in renal inflammation and cell death, GAS5 interfered with the expression of ECM proteins, collagen type I and fibronectin, to alleviate TGFβ-induced renal fibrosis." (PMID 39239549, 2024). "Finally, in renal fibrosis independent of diabetes, GAS5 has been demonstrated to mitigate TGF-β1-induced fibrosis by modulating miR-142-5p through the Smad3 pathway." (PMID 39941145, 2025).
stomach cancer (7 papers, 2015 to 2025). "For instance, the expression of GAS5 is found to be lowered in gastric tumors, contrary to the up-regulated expression of mir-23a." (PMID 31572428, 2019). "Compared to PTENP1-AS, the GAS5 expression was predominantly upregulated in the gastric tumor samples and the expression level was comparatively higher than competing mRNA AGO4." (PMID 29719612, 2018). "Consistent with our data, the lncRNAs H19, GAS5, TUG1, AP5M1, and MALAT1 were found to be overexpressed in TCGA database gastric tumors." (PMID 29719612, 2018). "Consistent with our results, we also found overexpression of lncRNAs such as H19, GAS5, TUG1, AP5M1 and MALAT1 and downregulation of LINCROR, POU3F3, HOTAIR, FALEC, NBAT1, and ZEB2-AS1 lncRNAs in TCGA gastric tumor datasets." (PMID 29719612, 2018).
acute myeloid leukemia (6 papers, 2020 to 2024). Acute myeloid leukemia (AML) is a group of neoplasms arising from precursor cells committed to the myeloid cell-line differentiation. "According to Yan and colleagues, patients with GAS5 rs55829688 CC genotype exhibited higher GAS5 expression and were associated with poor prognosis in acute myeloid leukemia." (PMID 35736636, 2022). "At the same time, a recently discovered polymorphism in GAS5 was found to be linked with poor prognosis in acute myeloid leukemia (AML) patients." (PMID 33076450, 2020). "Expression of GAS5 was upregulated in patients with acute myeloid leukemia (AML) and the GAS5 rs55829688 CC genotype; the promoter activity of GAS5 was increased through interaction with TP63, which in turn led to a worse prognosis for AML." (PMID 32354045, 2020).
Alzheimer disease (6 papers, 2014 to 2025). A progressive, neurodegenerative disease characterized by loss of function and death of nerve cells in several areas of the brain leading to loss of cognitive function such as memory and language. "Most recently, in Alzheimer’s disease (AD) studies, GAS5 has been found to be significantly upregulated in disease models and patient samples, where it exacerbates pathogenesis by acting as a ceRNA, sponging miR-23b-3p." (PMID 39941145, 2025). "The study demonstrates that lncRNA GAS5 is decreased in aged and Alzheimer’s disease brain." (PMID 36609440, 2023).
bladder urothelial carcinoma (6 papers, 2017 to 2023). "The Cancer Genome Atlas validation cohort analysis demonstrated that the expression of GAS5 in female patients with bladder urothelial carcinoma (BLCA) with larger tumor size was much lower than that in patients with a smaller tumor size (p = 0.041)." (PMID 32354045, 2020). "We evaluated the expression levels of different transcripts of GAS5 in 43 pairs of bladder urothelial carcinoma samples and their adjacent normal bladder tissues from BC patients at different stages." (PMID 29445179, 2018). "In conclusion, GAS5 tumour-suppressor lncRNA is significantly downregulated in bladder urothelial carcinoma, to the extent that it is able discriminate bladder tumours from the normal bladder urothelium." (PMID 30374124, 2018). "In bladder transitional cell carcinomas (BTCC), GAS5 expression is reduced and the patient’s prognosis worsens." (PMID 35837102, 2022). "In addition, levels of GAS5 in 274 male bladder urothelial carcinoma tissues did not correlate with tumor size status." (PMID 32354045, 2020).
Hepatic steatosis (6 papers, 2020 to 2025). Steatosis is a term used to denote lipid accumulation within hepatocytes. "Gas5 knockdown attenuated HFD-induced hepatic steatosis, reduced plasma triglyceride and cholesterol levels, and inhibited alanine aminotransferase and aspartate aminotransferase activities, all of which contributed to the reduced severity score of MASLD." (PMID 39872125, 2024). "Liver-specific GAS5 overexpression in mice accelerated weight gain and TG accumulation, gradually developing severe hepatic steatosis and hepatocellular ballooning." (PMID 35957809, 2022). "GAS5 knockdown attenuated HFD-induced hepatic steatosis, and this attenuation was reversed by miR-29a-3p inhibitor." (PMID 35322757, 2022). "GAS5 knockdown attenuated HFD-induced hepatic steatosis and lipid accumulation and reduced NAFLD activity score in HFD mice." (PMID 35322757, 2022). "LncRNA GAS5 knockdown attenuated HFD-induced hepatic steatosis, and this attenuation was reversed by the miR-29a-3p inhibitor; thereby providing vital evidence to establish the function of lncRNA GAS5 in the pathogenesis of NAFLD and its progression by targeting miR-29a-3p in vivo." (PMID 40868128, 2025). "In both in vitro and in vivo models of fatty liver, GAS5 was activated." (PMID 40868128, 2025). "As shown in, the HFD-induced hepatic steatosis was attenuated by t GAS5 knockdown in the HFD mice." (PMID 35322757, 2022). "GAS5-knockdown by tail vein injection of lentivirus containing shGAS5 led to GAS5 inhibition in the livers of HFD mice, accompanied with improved liver steatosis and reduced serum levels of ALT, AST, TCHO and triacylglycerol." (PMID 36555704, 2022). "Gas5 was found to sponge miR-29a-3p and suppressed its negative regulation on the neurogenic locus notch homologue protein 2 (Notch2), a known promoter of hepatic steatosis, leading to the upregulation of Notch2." (PMID 39872125, 2024). "Reduced p-CREB expression exacerbates HFD-induced hepatic steatosis by downregulating PPARα, whereas activated p-CREB reduces PPAR-γ expression to regulate the hepatic DNL, which was confirmed by the downregulation of DNL-related ACC1 and FAS in GAS5 knockdown cells." (PMID 35957809, 2022).
multiple myeloma (6 papers, 2015 to 2026). "They showed a dysregulation of plasma lincRNA-p21 levels in CLL patients and taurine upregulated gene 1 (TUG1), metastasis associated lung adenocarcinoma transcript 1 (MALAT1), HOX transcript antisense RNA (HOTAIR) and GAS5 in multiple myeloma patients." (PMID 33593440, 2021). "Many lncRNAs, such as MALAT1, GAS5, DLEU2, and H19, have been reported to be involved in the diagnosis and progression of multiple myeloma (MM)." (PMID 36607351, 2023). "Isin and colleagues reported that several circulating LncRNAs including TUG1, LincRNA-p21, MALAT1, HOTAIR, and GAS5 could be the potential biomarkers for diagnosis of chronic lymphocytic leukemia (CLL) and multiple myeloma (MM)." (PMID 26221732, 2015).
Obesity (6 papers, 2020 to 2025). Accumulation of substantial excess body fat. "The expressions of GAS5, fat mass and obesity-associated protein (FTO), insulin-like growth factor 2 mRNA-binding protein 2 (IGF2BP2), and Quaking (QKI) were assessed by quantitative reverse transcription-polymerase chain reaction (qRT-PCR) and western blot." (PMID 38782769, 2024). "In this study, we analyzed the expression levels of the lncRNAs: HOTAIRM1, GAS5, OIP5-AS1, and MZF1-AS1 from whole blood of healthy, obese, allergic asthmatic and obesity-related asthmatic adolescents through RT-qPCR." (PMID 37047453, 2023).
oral cancer (6 papers, 2017 to 2025). "Recently, the SNPs of GAS5 were found to be associated with the clinical characteristics of oral cancer and prostate cancer." (PMID 35456391, 2022). "In conclusion, the GAS5 SNP rs145204276 variant is related to poor-differentiation cell status in oral cancer." (PMID 33925911, 2021). "The expression of the GAS5 SNP rs145204276 variant (Ins/Del or Del/Del) is correlated with the poor-differentiation cell type of oral cancer for males in the current study." (PMID 33925911, 2021). "In conclusion, the presence of the GAS5 SNP rs145204276 variant is correlated with a poor-differentiation cell status in oral cancer in males." (PMID 33925911, 2021). "In the current study, we found the GAS5 SNP rs145204276 variants (Ins/Del or Del/Del) are related to a poor-differentiation cell character of oral cancer in a male population." (PMID 33925911, 2021). "Additionally, GAS5 SNP rs145204276 (Ins/Del or Del/Del) variants are associated with a higher risk of moderate to poor cell differentiation in oral cancer." (PMID 39744492, 2025). "Interestingly, the GAS5 SNP rs145204276 Del/Del variant is also correlated with poor-differentiation cell status and a worse tumor stage, as well as a larger tumor size in oral cancer based on our previous study." (PMID 35456391, 2022). "Similarly, in oral cancer, GAS5 single nucleotide polymorphism (SNP) rs145204276 variants (Ins/Del or Del/Del) were associated with poor differentiation cell status in male patients." (PMID 35736636, 2022). "However, the patients with GAS5 SNP rs145204276 variants (Ins/Del or Del/Del) showed a higher tendency of moderate to poor cell differentiation of oral cancer (OR: 1.454, 95% CI: 1.041–2.031, p = 0.028)." (PMID 33925911, 2021). "However, potential genetic variants in GAS5 that affect the susceptibility and progression of oral cancer have rarely been explored." (PMID 33925911, 2021). "Further randomized-controlled trials to evaluate whether the GAS5 SNP rs145204276 variant will affect the treatment outcome of oral cancer are mandatory." (PMID 33925911, 2021). "In this study, two loci of GAS5 single nucleotide polymorphisms (SNPs) (rs145204276 and rs55829688) were genotyped by using the TaqMan allelic discrimination in 1125 oral cancer patients and 1195 non-oral-cancer individuals." (PMID 33925911, 2021). "Consequently, it is possible that the SNP of GAS5 may be associated with the development of oral cancer in a specific gender, which was partially supported by the findings of the current study." (PMID 33925911, 2021). "The long noncoding RNA, Growth arrest-specific 5 (GAS5) plays a crucial role in the development of oral cancer." (PMID 33925911, 2021). "The GAS5 SNP rs145204276 Del variant increases the expression of GAS5 mRNA, which proven in the previous research, and the higher concentration of GAS5 may have a prominent effect on the development of oral cancer." (PMID 33925911, 2021). "The purpose of the current study is to evaluate whether the distribution of GAS5 SNP will affect the clinicopathological characters of oral cancer in a male population." (PMID 33925911, 2021). "Since the expression of GAS5 and its SNP influences the clinical characters in many neoplasms, it may also affect the clinical course of oral cancer for each gender, but this has rarely been evaluated in detail." (PMID 33925911, 2021). "In the subgroup analysis of the oral cancer population without alcohol drinking, the presence of the GAS5 SNP rs145204276 variant is correlated with the advanced cancer stage and larger tumor size." (PMID 33925911, 2021). "The other clinicopathological characteristics of oral cancer, including lymph node invasion, distal metastasis and cell differentiation, did not relate to the presence of GAS5 SNP rs145204276 variants (all p > 0.05)." (PMID 33925911, 2021).
oral cancer (continued). "The previous study only surveyed the protective effect and related pathway of the general GAS5 phenotype against oral squamous cell carcinoma, while certain SNPs may change the effect of GAS5 on oral cancer." (PMID 33925911, 2021). "Furthermore, a worse tumor stage and tumor size was found in the non-alcohol-drinking group with oral cancer and the GAS5 SNP rs145204276 variant." (PMID 33925911, 2021). "On the other hand, the severity of lymph node invasion and distal metastasis did not alter with different GAS5 SNP rs145204276 in both the whole group and subgroup analysis, which may indicate the universally minimal effects of GAS5 SNP in the two clinical characters for oral cancer." (PMID 33925911, 2021). "The similar outcomes in our study and the database of TCGA should further strengthen the relationship between GAS5 SNP rs145204276 and the three clinicopathological characteristics of oral cancer, which may be because of a carcinogenic effect of GAS5 SNP rs145204276." (PMID 33925911, 2021). "Besides, the presence of the GAS5 SNP rs145204276 variant is associated with a worse tumor stage and tumor size in oral cancer patients without alcohol drinking." (PMID 33925911, 2021). "This phenomenon may imply that the GAS5 polymorphism is not a risk factor for oral cancer development in a normal population, but rather a predisposing factor for tumor progression in those with pre-existing oral cancer." (PMID 33925911, 2021). "In addition, the distribution of GAS5 SNP between patients with oral cancer and non-oral-cancer individuals was also analyzed." (PMID 33925911, 2021). "Moreover, the same GAS5 SNP is correlated with both the advanced tumor stage and larger tumor size of oral cancer in patients without alcohol consumption." (PMID 33925911, 2021). "Moreover, the genotypes of GAS5 SNP rs55829688 did not influence the clinicopathological characteristics of oral cancer (data not shown)." (PMID 33925911, 2021).
abdominal aortic aneurysm (5 papers, 2019 to 2024). Enlargement and ballooning of the vessel that supplies arterial blood to the abdomen, pelvis and legs. "Just as LncRNA GAS5 inhibiting apoptosis of SMC to become a strategy against abdominal aortic aneurysm (AAA) 57 and miR-27a targeting apoptosis of ECs and strongly diminishing occurrence of aortic dissection (AD) 58, Stabilizing Kindlin-2 might potentially serve as a novel strategy against CIPO." (PMID 32483447, 2020). "Another study showed that lncRNA growth-arrest-specific transcript 5 (GAS5) induced SMC apoptosis and subsequent abdominal aortic aneurysm (AAA) by activating the zeste homolog 2 (EZH2)-mediated RIG-I signaling pathway in angiotensin II-induced AAA mouse models." (PMID 35693778, 2022).
cardiac hypertrophy (5 papers, 2021 to 2023). "Notably, Gas5 and Sghrt (previously annotated as 1810058i24Rik) have been implicated in cardiac hypertrophy in a rat model, and certain regulatory lncRNAs appear to influence cell cycle arrest." (PMID 38110334, 2023). "LncRNA GAS5, as previously noted, can enhance heart function and even cure signs of myocardial hypertrophy in DCM mice by suppressing NLRP3 activation." (PMID 37396588, 2023). "In summary, our study demonstrates that OT ameliorates cardiac hypertrophy by inhibiting PI3K/AKT pathway via lncRNA GAS5/miR-375-3p/KLF4 axis." (PMID 34925023, 2021). "In our preliminary experiments, we detected that OT ameliorated cardiac hypertrophy induced by ISO along with lncRNA GAS5 remarkably upregulated, as well as miR-375-3p down-regulated." (PMID 34925023, 2021). "The findings showed that OT significantly attenuated cardiac hypertrophy, increased expressions of lncRNA GAS5 and KLF4, and decreased miR-375-3p expression." (PMID 34925023, 2021). "A study showed that GAS5 improved cardiac function and myocardial hypertrophy in DCM mice." (PMID 37396588, 2023). "LncRNA Growth inhibitor-specific transcript (GAS5) has been reported to regulate various cardiac functions through pyroptosis, such as inhibition of cardiac hypertrophy, reduction of cardiac fibrosis and improvement of myocardial ischemia and hypoxia leading to cardiac dysfunction." (PMID 37396588, 2023). "The expressions of cardiac hypertrophy markers (B-Natriuretic Peptide, BNP and β-myosin heavy chain, β-MHC), long non-coding RNA Growth (LcRNA) Arrest-Specific transcript 5 (lncRNA GAS5), miR-375-3p, and Kruppel-like factor 4 (Klf4) were detected by qRT-PCR." (PMID 34925023, 2021). "Our study revealed the role of lncRNA GAS5 and KLF4 in cardiac hypertrophy in an in vitro model, not in an in vivo one." (PMID 34925023, 2021). "In addition to validating known EZH2-binding ncRNAs (e.g., Gas5, Meg3, and Malat1), our findings reveal a large panel of novel ncRNAs involved in the dynamic regulation of the EZH2 function during AngII-induced cardiac hypertrophy." (PMID 33732733, 2021).
Cerebral ischemia (5 papers, 2019 to 2023). Restriction of arterial blood supply to the brain associated with insufficient oxygenation to support the metabolic requirements of the tissue. "Knockdown of GAS5 was also shown to reduce apoptosis and inflammation in cerebral ischemia/reperfusion injury through interaction with miR-26b-5p and the regulation of Smad1 expression." (PMID 38132140, 2023). "Meanwhile, YY1 adversely modulates GAS5 expression by binding to the GAS5 promoter and thus represses its transcription in neurons following cerebral ischemia/reperfusion injury." (PMID 34497757, 2021). "Furthermore, increasing number of studies have found that GAS5 plays critical role in cerebral ischemia." (PMID 31434993, 2019). "In the cerebral ischemia/reperfusion (CI/R) model, YY1 binds to lncRNA GAS5 to form a complex that fosters PFKFB3 transcription, glycolysis, and neuronal apoptosis." (PMID 37184686, 2023). "Therefore, we provide evidence that miR-146a-5p molecular sponge GAS5 is destroyed by STV-Na, and that STV-Na is increasingly considered as a potential drug for the treatment of cerebral ischemia." (PMID 31434993, 2019).
esophageal squamous cell carcinoma (5 papers, 2018 to 2024). Esophageal squamous cell carcinoma (ESCC) is a type of esophageal carcinoma (EC) that can affect any part of the esophagus, but is usually located in the upper or middle third. "In fact, investigation in esophageal squamous cell carcinoma also supports that GAS5 is an ISG which regulates the expression of other ISGs." (PMID 31200545, 2019). "In fact, GAS5 was also reported to positively regulate IFN responses in esophageal squamous cell carcinoma." (PMID 31200545, 2019).